MYC (MYC proto-oncogene, bHLH transcription factor)
Diseases named in the same sentence as MYC in open-access papers (continued):
Sharing a sentence is not in itself a finding about the gene and the disease.
tumor (continued). "Pharmacologic targeting of CDK9 has shown promising in vitro and in vivo anti-tumor activity in malignancies that exhibit dependence on Mcl-1 and/or MYC." (PMID 36998071, 2023). "Increased in GSCs, YTHDF2 plays a vital role in stem maintenance, and it enhances tumour growth in mice through stabilising MYC (YTHDF2-MYC) and targeting IGFBP3." (PMID 36831575, 2023). "Recent studies have also demonstrated that MYC signaling can enable tumor cells to dysregulate the TME and evade the host immune response." (PMID 37998757, 2023). "Numerous studies sustained a chemoresistance in tumor cells expressing high levels of MYC and activation of WNT signaling pathway." (PMID 37869102, 2023). "In fact, several compounds that either directly or indirectly target c-MYC exert anticancer properties in preclinical tumor models." (PMID 37111592, 2023). "TTP is involved in the promotion of MYC-mediated tumor proliferation, while HuR overexpression increases tumor size and weight in mice, which is related to HuR’s regulation of the spliceosome, RNA transport, and the cell cycle." (PMID 37179344, 2023). "This implicates Sirt2’s involvement in HCC glucose metabolism, potentially shifting focus away from the promotion of MYC stability to the Warburg effect as the major mechanism to explain the tumor phenotype." (PMID 37628798, 2023). "Recent studies have demonstrated that MYC forms multimeric structures in response to perturbations, affecting its interactome and enabling tumor cells to proliferate under stressful conditions, limiting DNA double-strand break formation during S-phase." (PMID 37755397, 2023). "Immunohistochemical analysis of tumor tissues showed that MYC expression was downregulated after KDM4B knockdown, while FBXL3 and CRY2 expression was upregulated." (PMID 38093312, 2023). "MYC plays a significant role in promoting the recruitment of immunosuppressive cells within the tumor microenvironment, including regulatory T cells (Treg)." (PMID 37755397, 2023). "For example, when MYC is overactivated, it can promote glycolysis in tumor cells, which results in a low-glucose environment." (PMID 36966168, 2023). "Hyperactivation of MYC initiates tumor-induced immune suppression through crosstalk between tumor cells and different immune cell subsets in the TME, such as T cells, B cells, macrophages, natural killer cells, dendritic cells (DCs), and neutrophils." (PMID 36966168, 2023). "MYC activity was seen to increase with disease progression from normal tissue (gray) to tumor-adjacent benign tissue (orange), to primary tumor (light blue), and more malignant disease stages." (PMID 37399401, 2023). "LNPs have been proven useful for the delivery of interfering RNAs to inhibit the growth and viability of MYC-dependent tumor cell lines or tumors." (PMID 36969025, 2023). "In contrast to the L. ledebourii extract, doxorubicin significantly induced the transcript level of the MYC in the tumor and normal cell lines." (PMID 38106631, 2023). "Oncogenic c-MYC and its paralogues orchestrate tumor-promoting signaling through reprograming of cell growth, survival, metabolism, and shaping the tumor microenvironment (TME) and tumor immunity." (PMID 36765581, 2023). "Similar patterns have been seen for WT, where AURKA inhibition impaired tumor growth and induced apoptosis both in vitro and in vivo; however, such effects were improved in RB1-deficient cell lines compared to those with MYC amplification." (PMID 36839989, 2023). "The active targeting of nanoparticles into MYC-dependent tumor cells or specific intracellular compartments can be achieved by appropriate surface modifications that are relevant to the development of next-generation nanoparticles." (PMID 36969025, 2023).
tumor (continued). "In non-small cell lung cancer, lncRNA HIF1A-As2 forms a positive feedback loop with MYC, driving cell proliferation and tumor metastasis." (PMID 37755396, 2023). "It has been shown that MYC directly regulates genes involved in cell migration, invasion, cell cycle progression, and tumor microenvironment leading to metastasis." (PMID 37444499, 2023). "Omomyc, a well-known inhibitor, is a mutant mini-peptide with a basic helix–loop–helix structure that sequesters MYC in an inactive complex, preventing MYC-induced tumorigenesis in multiple mouse tumor models." (PMID 37755397, 2023). "Experimental evidence has demonstrated that inhibiting MYC expression can reverse tumorigenesis, providing a proof of concept for the pharmacological targeting of this oncoprotein to impede tumor cell growth." (PMID 37755397, 2023). "One key aspect of MYC’s programming of the tumor microenvironment is its ability to stimulate angiogenesis, the formation of new blood vessels." (PMID 37755397, 2023). "If suppression of c-MYC by miR-616 is indeed crucial for the tumor-suppressive effects of miR-616, overexpression of c-MYC should rescue the effect of miR-616 on cell growth." (PMID 37685841, 2023). "Through their ability to negatively regulate the PI3K-AKT, p70/p85 S6K, ERK/MAP kinase, and the c-MYC pathways, methylation-sensitive PP2A enzymes are thought to act as tumor-suppressors, whose downregulation/mutation promotes tumorigenesis." (PMID 37644036, 2023). "Immunohistochemical analysis of tumor tissues showed that modulation of MSI2 in tumor cells had a direct relationship to MYC expression level." (PMID 37117191, 2023). "The tumor suppressor MXI1 was supposed to inhibit MYC levels by binding to the promoter of MYC; however, a large amount of miR-155 and miR-23a binds to the 3′UTR of MXI1, causing a decrease in its expression." (PMID 38125749, 2023). "On the other hand, multiple studies described an increased activity of the proto-oncogene MYC mediated by p300 in other tumor entities." (PMID 37659057, 2023). "Taken together, MYC regulated a range of tumor cell–intrinsic and –extrinsic biological processes associated with mTORi response and thus governed mTORi resistance." (PMID 37642941, 2023). "Despite these obstacles, recent pharmaceutical-based strategies have emerged to target MYC and hinder tumor growth." (PMID 37755397, 2023). "Consistent with this, SHMT2 silencing remarkably suppressed the m6A levels of MYC in nude mice tumor tissues." (PMID 37932821, 2023). "We analyzed tumor sections from patients with MYC amplified Group 3 MB as well as a patient‐derived orthotopic xenograft (PDOX) utilizing the BT52CTC patient cells and confirmed expression of LIN28B in these tumors." (PMID 37341142, 2023). "As an oncogenic transcription factor, c-MYC and its paralogues transcriptionally regulate hundreds of genes that impact tumor metabolism and enable tumor progression." (PMID 36765581, 2023). "To address this shortcoming, we set out to study the local metabolic effects of the oncogene c-MYC, a pleiotropic transcription factor that accumulates with tumor progression and influences metabolism." (PMID 37946084, 2023). "In this sense, it has been previously shown that constitutive upregulation of c-MYC and KLF4, as seen in TNF-α + E1 exposed HeLa cells, is associated with CSC enrichment and tumour aggressiveness." (PMID 36674737, 2023). "Each subtype of MYC exhibits unique features, leading to distinct oncogenic mechanisms in tumor development." (PMID 38021164, 2023). "On the other hand, the relative tumor area in hep-c-MYC/AR-FL male mice were morphologically larger than that in hep-c-MYC male mice." (PMID 36746917, 2023). "Through subsequent screening of PVT1::MYC with FusionInspector, we identify a total of 32 samples (+9 TCGA tumor, +1 TCGA normal, and +3, −1 GTEx)." (PMID 37323575, 2023). "Since MYC is often dysregulated in many types of cancer, it is an attractive target for tumor treatments." (PMID 37443779, 2023).
tumor (continued). "Based on the in vitro data, we next determined the influence of MSI2 on the expression of MYC proteins in xenograft tumor tissues." (PMID 37117191, 2023). "For example, recurrent amplification of oncogenes such as MYC, ERBB2 (HER2), and FGFR1, and significant loss of tumor suppressors such as CDKN2A and CDKN2B were observed in the high-CRRS group." (PMID 36936912, 2023). "Its mammalian homologue, MYC, is overexpressed and/or activated in 50–60% of all cancers, promoting tumor initiation and progression." (PMID 36609617, 2023). "The expressions of c-MYC, AR-V7, and AR-FL in the developed tumor foci were confirmed by immunohistochemistry at 20 days post-injection (dpi)." (PMID 36746917, 2023). "The development of small molecule inhibitors that disrupt MYC/MAX heterodimerization further emphasized the importance of promoting MYC degradation to suppress tumor growth and enhance immunotherapy." (PMID 37400551, 2023). "It is reported that in many tumor cell lines including B lymphoma, the metabolism of glutamine is modulated by MYC via increasing the expression of GLS." (PMID 37367892, 2023). "The apparently undruggable MYC protein structure promoted the development of alternative inhibiting principles to achieve desirable anti-tumor effects." (PMID 36969025, 2023). "Similar to the results at the cellular level, here we found that mRNA nano-lantern promoted the expression of Smad4 protein in tumor tissues and induced the decline of MYC, VEGFC, and CXCL5." (PMID 36894556, 2023). "MYC is a key oncogenic driver in multiple tumor types, but concomitantly endows cancer cells with a series of vulnerabilities that provide opportunities for targeted pharmacological intervention." (PMID 37158102, 2023). "HIPEC treatment restored the tumor suppression activity of the network comprising miR-145-5p and its target genes MYC, EGFR, MUC1, and OCT4." (PMID 37598177, 2023). "We conclude that MYC is sufficient to regulate the CSF1 expression in the OS tumor, which orchestrates the migration of macrophages in the TME of OS." (PMID 37279073, 2023). "Functionally, TRAP1 was shown to directly promote the activity of the electron transport chain to facilitate cellular respiration in low-nutrient conditions and to promote MYC-dependent tumor cell migration." (PMID 37508418, 2023). "Accumulating evidence revealed that c-MYC is a critical regulator of the tumor microenvironment (TME), and involved in the stromal cell growth and angiogenesis." (PMID 36721232, 2023). "Transcription factors (TFs) associated with tumor metastasis and progression, such as MITF, MYC, and CTNNB1, showed high transcription activity in the MYC+MEL subcluster." (PMID 38065972, 2023). "In mice with MYC-induced hematological cancers, an inactivation of the MYC transgene led to tumor regression." (PMID 37570631, 2023). "Together, these data demonstrated that prolonged inhibition of mTOR fosters the genomic evolution of tumor cells resulting in the amplification and upregulation of MYC." (PMID 37642941, 2023). "We also examined the expression of target genes of NF-kB pathway, including BCL2, MYC, and CCND1, which are also associated with tumor proliferation." (PMID 37716704, 2023). "In tumor cells, other signaling pathways often interact with MYC to provide strong support for tumor progression, especially the WNT/β-catenin pathway." (PMID 36966168, 2023). "MYC initiates tumorigenesis, which results from tumor-intrinsic mechanisms that regulate different cellular processes, including cell proliferation and apoptosis." (PMID 37444499, 2023).
tumor (continued). "GSVA enrichment analysis showed that m5C-associated lncRNAs were significantly associated with pathways related to tumor progression, such as KRAS signaling pathway, PI3K-AKT-mTOR signaling pathway, MYC targets and TGF-BETA signaling pathway, and so on." (PMID 37670275, 2023). "Recent studies elucidate the role of MYC in TME modulation as well as in the host immune response in multiple tumor types." (PMID 37279073, 2023). "The major findings include overall restricted tumor growth using a novel transgenic approach and new evidence that c-MYC’s stability and localization to the nucleus are mediated by Sirt2 deacetylation." (PMID 37628798, 2023). "Two lactate-related genes, namely secreted phosphoprotein 1 (SPP1) and MYC proto-oncogene (MYC), are upregulated by > 4-fold in the tumor samples; in fact, SPP1 has the highest change, 16-fold." (PMID 36091047, 2022). "CMS2 tumor epithelial cells also showed gene expression driven by copy number alterations in the MYC and DNA repair genes." (PMID 35538548, 2022). "In summary, we show that MYCMI-7 is a direct MYC-binding compound that potently and selectively inhibits MYC:MAX interaction and MYC-mediated gene regulation and tumor cell growth in a MYC-dependent manner in culture and in vivo, while sparing normal cells." (PMID 36874405, 2022). "In most tumors, MYC is a transcription factor; as an oncogene, MYC promotes tumor cell proliferation and metastasis." (PMID 36059961, 2022). "A significant correlation (R 0.493; Fisher exact test p = 0.006) was observed for the MYC activity score and the percentage of tumor cells staining positive for MYC in the HOVON-84 cohort." (PMID 35267654, 2022). "Myc is also a target for miR-449c-5p and circNOTCH1, upregulated in gastric cancer and promotes tumor growth and metastasis by interfering with miR-449c-5p/MYC/NOTCH1 axis." (PMID 35626752, 2022). "The aberrant expression and dysregulation of AMBRA1 positively and negatively control tumor formation and progression through diverse signal pathways, such as c-MYC, cyclin D, mTOR, PI3K, STAT3, and TGFβ." (PMID 36237336, 2022). "The findings revealed that the LMR-lncRNA signature was primarily involved in MYC targets, glycolysis, hypoxia, and tumor-related signaling pathways." (PMID 35422758, 2022). "Our findings show that TCH-165 effectively reduces MYC protein levels in cell culture, inhibits cancer cell proliferation, and inhibits tumor growth in vivo." (PMID 35625675, 2022). "MYCMI-7 potently induces growth arrest/apoptosis in tumor cells in a MYC/MYCN-dependent manner and downregulates the MYC pathway on a global level as determined by RNA sequencing." (PMID 36874405, 2022). "We conclude that MYC overexpression can manipulate IFN signaling by reducing the expression of a broad network of genes in our murine tumor model." (PMID 36323660, 2022). "Its potential tumour suppressive activity was attributed to targeting of the 3′-UTR of the c-MYC oncogene." (PMID 35159022, 2022). "RT-qPCR analysis of the same i-SOX2 tumor cell lines demonstrated that MYC mRNA levels were significantly downregulated when SOX2 was elevated." (PMID 35454854, 2022). "GSEA analysis revealed some tumor pathways associated with RGS20, namely DNA REPAIR, mTORC1, MYC TARGETS V1 signaling being predominant." (PMID 36009801, 2022). "In isolated CD31+ ECs from control and shFGF2 NPC tumor tissues, knockdown FGF2 in NPC tumor cells significantly reduced MYC expression in tumor-associated ECs." (PMID 35985991, 2022). "The oncogenic transcription factor MYC drives cell growth, differentiation and tumor development in many cancers." (PMID 35625675, 2022). "There was a significant correlation between the response to MYCMI-7 and the MYC mRNA/protein levels among the 60 tumor cell lines." (PMID 36874405, 2022). "Fundamentally, MYC participates in reprogramming glutamine metabolism to increase TCA activity in tumor cells." (PMID 35053485, 2022).
tumor (continued). "The impact of MYC is likely to be context dependent and the relationship between MYC activation and DNA repair in the human tumor environment requires further investigation." (PMID 35538088, 2022). "We also detected elevated expression of PVT1 in most tumor samples and gains in the MYC/PVT1 genomic locus in a third of the samples." (PMID 36139061, 2022). "When used together, CDK9 and BRD4 inhibitors impede transcription of anti-apoptotic genes and c-MYC oncogene, suppressing tumor proliferation." (PMID 35092513, 2022). "The overexpression of CACNA2D1, JUN, GNG4, NGF, MYC, and MAPK4K4, components of the MAPK pathway, is associated with tumor aggressiveness and chemotherapy resistance." (PMID 36344487, 2022). "The tumor-suppressive role of miR-196b is supported by the findings that it regulates MYC and ERG and that it binds the 3′-UTR region of IGFBP3 mRNA (reversible by resveratrol in vitro)." (PMID 36010971, 2022). "We found that in addition to the enrichment of its downstream targets, the MYC oncogene itself was significantly enriched in tumors, and its differential expression clearly distinguished tumor samples from controls." (PMID 36139061, 2022). "Accordingly, tumor resistance to immunotherapy was also shown to be acquired through tumor cell-intrinsic mechanisms, including loss-of-function of JNK and PTEN, MYC overexpression, and constitutive WNT signaling." (PMID 36124553, 2022). "In the CRC tissue samples, MYC expression was moderately correlated with tumor size (R = 0.43, p = 0.03) and pathological T (R = 0.60, p = 0.002)." (PMID 36052265, 2022). "In conclusion, MYCMI-7 treatment delayed onset of AML, decreased tumor burden, reduced MYC expression, and induced apoptosis and senescence markers in leukemic cells, but did not improve overall survival." (PMID 36874405, 2022). "In fact, Pan-cancer analyses of the tumor sequencing data from cancer genome atlas data, in 33 cancers, found that 28% of all samples had at least one of the MYC paralogs amplified." (PMID 35883689, 2022). "There has been an explosion of molecular, cellular, and animal experiments to illuminate the effect of MYC in the initial development of neoplasms." (PMID 35774514, 2022). "For instance, we examined the expression of Ifitm3 in our four single-cell tumor datasets and show that this gene is strongly expressed by all MYC subtypes." (PMID 35318328, 2022). "In our study, we found that PVT1 expression is increased in tumor samples and that it correlates with increased MYC expression." (PMID 36139061, 2022). "Hedgehog inhibitors (HHis) target the hedgehog pathway to decrease the expression of various proteins such as GLI family zinc finger 1 (GLI1), cyclins and MYC, which leads to reduced tumor cell survival, increased immune infiltration, and tumor remission." (PMID 36430669, 2022). "In IBC however, a different correlation pattern was observed (Rs = 0.115; P = 0.166), suggesting different interactions between ER and MYC depending on the tumor phenotype." (PMID 35042871, 2022). "MYC is one of the most dysregulated oncogenes and is thought to be fundamental to tumor formation and/or maintenance in many cancer types." (PMID 36018850, 2022). "MYC inactivation in mouse tumors downregulated PD-L1 expression and enhanced the anti-tumor immune response." (PMID 36582521, 2022). "Dysregulation of MYC clearance can induce its oncogenic transcriptional activity, resulting in the transcription of multiple tumor-promoting genes." (PMID 35625675, 2022).